CD14 (CD14 molecule)
Diseases named in the same sentence as CD14 in open-access papers (continued):
Sharing a sentence is not in itself a finding about the gene and the disease.
infection (continued). "Moreover, a subset of CD14+ cells with low HLA-DR expression have recently been reclassified as myeloid-derived suppressor cells, and expand during infection or inflammation where they are capable of suppressing T cell responses and induce CD4+ CD25+ Foxp3+ regulatory T cells." (PMID 23446058, 2013). "In addition to the inhibition of apoptosis previously reported in Leishmania-infected MDMs, we also report the unexpected finding that a sub-population of CD14+ human MDMs proliferate in response to Leishmania, as measured by BrdU incorporation at days 12–14 after infection." (PMID 22496656, 2012). "The infection with S. Typhimurium significantly increased TLR4, MD‐2, LBP, CD14, and MyD88 mRNA in both parts of the intestine." (PMID 41474380, 2026). "The immune activation stimulates proinflammatory Th1 cells and CD14+CD16+ monocytes, amplifying signaling pathways that recruit macrophages and neutrophils to the sites of infection." (PMID 41012171, 2025). "Indeed, chemotactic migration of CD14+ monocytes to the infection site and their transition into bactericidal macrophages, thus replenishing the exhausted mucosa-patrolling macrophages, represents one of the key mechanisms of innate immune defense to infection." (PMID 40105369, 2025). "CD206 + IM are involved in response to wounding and infection recovery and CD163 + CD206 + monocyte-derived IM have been shown to directly derive from extravasating, circulating CD14 + monocytes in another human immune system-engrafted mouse model." (PMID 40920821, 2025). "HCV infection elicits dynamic changes in hepatic myeloid cell subsets, particularly CD14+ and CD16+ macrophages, contributing to the entire pool of ISG and MHC-II genes expressed during infection." (PMID 41293057, 2025). "We identified a biphasic pattern of EV release—initial suppression during active infection followed by restoration during and after therapy—most notably affecting the CD4+ and CD14+ subsets." (PMID 40872281, 2025). "Individuals with HTNV infection possessed a higher proportion of M1-like monocytes (CD14++ CD16+) but a relatively lower M2-like percent (CD14+ CD16++) than those with Japanese encephalitis virus (JEV), hepatitis B or C virus (HBV or HCV) infection." (PMID 38200007, 2024). "At 2 h post-infection, E was predominantly detected on CD66+ granulocytes, CD14+ monocytes, and CD19+ B cells, with lower levels in CD56+ NK cells, CD3+ T cells, and CD41a+ platelets, in a dose-dependent manner." (PMID 39540772, 2024). "Data disclose that CD14 and CD44 are weakly expressed by hemocytes under basal conditions and thus their expression is inducible and modulated by infection." (PMID 38191588, 2024). "Perhaps studying isolated CD14+ monocytes as they differentiate in vitro deprives them of priming, resulting in a limited ability of the MDM to secrete IFN-I upon infection by Mtb." (PMID 38866980, 2024). "However, since our study was performed using bone marrow neutrophils, we do not rule out the possibility that elicited neutrophils may induce CD14 expression during infection or are able to reprogramme themselves to undergo TLR4-driven cell death at the site of infection." (PMID 38965211, 2024). "It is well established that infection of CD34+ progenitors and CD14+ monocytes with HCMV in which US28 has been deleted not only results in IE gene expression, but also in the production of infectious virus." (PMID 38287192, 2024). "Intermediate monocytes (CD14+CD16+) increased, while myeloid dendritic cells (mDCs) rather than plasmacytoid dendritic cells (pDCs) markedly declined during early infection." (PMID 37033979, 2023). "Overall, transcriptomic analysis of B, CD14+, CD4+ and CD8+ cells indicates that BTV infection starts altering the activity of these immune cells early in the infection (by day 3pi)." (PMID 37920474, 2023).
infection (continued). "The present study reveals a shrimp LvCD14L-Tolls-NF-κB signaling pathway like the CD14/TLR4/NF-κB signaling pathway in mammalians, which enriches the functional mechanism of secretory LRR-only immune receptors during pathogens infection in invertebrates." (PMID 37175476, 2023). "It thus appears that B, CD14+, CD4+, and CD8+ cells are capable of sensing the infection and, as a consequence, trigger the transcription of IFN-related genes." (PMID 37920474, 2023). "Taking the stage at which these CD14+ PMNs appear into account, the results indicated that CD14+ PMNs had a stronger ability to produce cytokines than their negative counterparts and could also negatively regulate the immune response at the recovery stage of infection progression." (PMID 37705063, 2023). "Following infection of BEAS-2B cells with RSV, we confirmed that RSV infection down-regulated miR-34b/c-5p, and up-regulated the expression levels of CXCL10 and CD14." (PMID 36829591, 2023). "The link between CD14 expression and IFN response is also supported by literature data on the infection of murine MΦs with VSV." (PMID 35203475, 2022). "In normal physiological conditions, 85% of the monocytes in the peripheral blood express CD14++ CD16 low HLA-DR++ phenotype and these cells leave the circulation and infiltrate to the inflammatory site following infection." (PMID 35898494, 2022). "In the context of markers of infection, an emerging molecule is SCD14-ST, the truncated form of soluble CD14." (PMID 35740951, 2022). "Comparable to infection with RuV, the expression of ORF3 of hepatitis E virus (HEV) reduced CD14 expression." (PMID 35203475, 2022). "Changes in the expression of multiple genes, such as CD14, INFB1, and CXCL10, varied with the infection duration." (PMID 36296238, 2022). "Next, we sorted patients based on the infection time (1-7 days after diagnosis of SARS-CoV-2 by PCR and 8-25 days after), and we observed the percentage of CD14+PD1+ cells increased along the time of infection." (PMID 35971391, 2022). "By implication, this supports our hypothesis on the contribution of a reduced CD14 expression level to maintenance of RuV in M-MΦs on a rather low inflammatory background as shown here through a reduced IFN expression level after blockage of CD14 prior to RuV infection." (PMID 35203475, 2022). "Notably, HM 1 and 2, and Cd14+ monocytes accounted for ~73% of all the microglia detected under homeostatic conditions, but IAMNP 1 and 2, and Mrc1+ BAMs subclusters progressively increased in frequency over the course of infection, suggesting an adoption of an infection-associated phenotype." (PMID 36180478, 2022). "Classical, CD14++CD16- monocytes are critical to the initial immune response to infection, as they are recruited to sites of infection and inflammation to recognize and phagocytose pathogens, secrete pro-inflammatory mediators, and recruit other immune cells." (PMID 35371104, 2022). "On day 3 after infection, when the most severe symptoms in both models appear, the combination of antibodies against IRF2 and CD14 resulted in the detection of a significantly increased monocyte population after E. histolytica infection." (PMID 36010615, 2022). "In the case of infection, LPS is extracted from bacterial membranes and bound to LPS binding protein (LBP), which transfers LPS through interaction with CD14 to toll-like receptor 4 (TLR4)." (PMID 35326484, 2022). "We observed decreased monocyte frequency in patients with moderate symptoms; however, when assessing CD14+PD1+ monocytes, we saw increased PD-1 in patients with severe and critical symptoms, being related to the longer duration of the infection." (PMID 35971391, 2022). "After 48 h of infection, the levels of TNF, CXCL8, IL6, CSF2, CD180, CD14, and CCL2 levels increased and those of IL-10, INFB1, and CXCL10 decreased." (PMID 36296238, 2022).
infection (continued). "The expression of CD11b, CD4, CD14, and CD68 for M0; IL-6, HLA/DRA, and CXCL10 for M21, and IL-10, CD163, fibronectin-1 or FN1, and CCL17 was evaluated by qPCR at 2 and 24 h after infection." (PMID 35889103, 2022). "At the beginning of the infection (1 h), despite the increase in TLR4 expression, there was a decrease in the expression of CD14 and LY96 (also known as MD-2), which are important for lipopolysaccharide recognition." (PMID 36296238, 2022). "We observed increased expression of the CD14 and FN1 genes following BCG, H37Ra and H37Rv infection, confirming their critical role in M.tb infection." (PMID 34632719, 2021). "CD3+CD4+ T cells, CD3+CD8+ T cells and CD45+CD14+ monocytes were present in reconstituted mice, suggesting that HuPBL-NCG mice harbored the major cellular targets for SFTSV infection." (PMID 33974679, 2021). "It was noteworthy that the higher severity of the infection led to significant decreases of CD235a+, CD45+, CD19+, and CD14+ EVs levels." (PMID 33925492, 2021). "Conversely, the HLA-DR+ component, composed of both CD14+ and CD16+ monocytes, was elevated during active infection and remained high during recovery." (PMID 33691089, 2021). "Other immune regulatory molecules, such as CD14 and CSF2, were significantly up‐regulated, while others, such as TLR4, IRF9 and CD36, were significantly down‐regulated after infection with H37Rv." (PMID 34632719, 2021). "Within the innate cellular compartment, the strongest correlations (Spearman) with GA were increasing frequencies of granulocytes and CD14+CD16- classical monocytes (cMCs), which are front-line defenders that rapidly respond to injury or infection." (PMID 34497610, 2021). "As the first line of the cellular immune response, neutrophils and monocytes recruited to the site of tissue damage and/or infection, are divided into three different subsets according to their CD16/CD62L and CD16/CD14 expression, respectively." (PMID 34575249, 2021). "On one hand, six of these biomarkers (CD14, HVEM, IL-6, B7.1, Siglec-10, and HIF-1α) were related to both HIV exposure and infection, presenting significantly higher expression in both the HIV+ and HEU groups than in the UU group." (PMID 34211989, 2021). "In agreement with our previous results, OROV antigens were detected in monocytes (MC, CD14+), dendritic (DC, CD11c+ CD11b+) and polymorphonuclear (PMN, CD11c+CD11bneg) cells after infection of peripheral blood cells from healthy donors (Supplementary S4A)." (PMID 32708342, 2020). "The significant population consisted of resident CD14-positive cells, likely microglia, in the DENV-infected mouse brains, which increased at 6 d.p.i. but remarkably decreased at 8 days post-infection." (PMID 33072626, 2020). "Sustained changes seen here include an increased proportion of classical (CD14+CD16−) monocytes and reduced proportions of non‐classical (CD14−CD16+) monocytes in the periphery until at least day 45 following infection." (PMID 32566226, 2020). "We found that infection with the wild-type S. Typhimurium upregulated mRNA in the terminal ileum in all analyzed members of the TLR4 signaling pathway—TLR4, MD-2, CD14, and LBP." (PMID 32842482, 2020). "HCMV maintains latency within CD14+ monocytes and CD34+ cells of the myeloid lineage, but only after primary infection and dissemination, which is thought to occur through productive infection of oral epithelial cells." (PMID 32714883, 2020). "CD14, CD38, and Abca1 “triple positive” (TP) cells had not only the highest infection rates and bacterial loads, but also a strong interferon-γ signature and nitric oxide synthetase-2 production indicating recognition by T cells." (PMID 32544188, 2020). "The functional analyses uncovered the ability of TLR2/6/CD14 to sense DENV infection and to drive infection-mediated inflammatory responses leading to activation of human vascular endothelium." (PMID 32576819, 2020).
infection (continued). "One study found that, through infection of THP-1- and CD14-positive primary human monocytes, HHV8 upregulates the TLR3 pathway and induces TLR3-specific cytokines and chemokines, including beta 1 interferon (IFN-β1) and CXCL10 (IP-10)." (PMID 33519292, 2020). "We observed that both PD-L1 on CD14+ cells and PD-1 on CD8+T cells were highly expressed at the site of infection in pleurisy TB patients’ effusion samples (PEMC)." (PMID 30655556, 2019). "Circulating CD14+ monocytes are commonly used as a model of latent infection in vitro, with HCMV establishing a quiescent infection in them that is capable of reactivating in response to differentiation and stimulation of the cells." (PMID 29547547, 2018). "CD15+ granulocyte depletion from blood prior to infection with M. tuberculosis-lux impaired control of mycobacteria by 96 h, with a greater effect than depletion of CD4+, CD8+, or CD14+ cells (p < 0.001)." (PMID 29755473, 2018). "Ab4ΔORF1/71 infection had reduced nasal shedding (1/5 vs. 5/5) and, simultaneously, decreased intranasal interferon (IFN)-α, interleukin (IL)-10 and soluble CD14 secretion." (PMID 30440016, 2018). "In two additional samples tested at 7 days post-infection HIV was detected in CD4 T cells and still detected in CD14+ cells." (PMID 30532754, 2018). "Our findings are consistent with a previous study, which used immunohistochemistry to detect HIV in human cervix 7 days post-infection and reported that HIV p24 Ag+ cells were predominantly CD14+/CD68+ cells and only a few were CD3+ T cells." (PMID 30532754, 2018). "Then, 24 hours post infection (hpi), the amount of GFP positive cells in various PBMC sub-populations that was defined via staining of the surface markers CD14, CD19, CD3, CD4, CD8 and CD56, followed by flow cytometry analysis." (PMID 29367743, 2018). "Surprisingly, we found that the total number of MDSCs (defined as the sum of CD14+ MDSC and Lin-CD15+MDSC) in BM was paradoxically decreased 14 months after SIVmac251 infection." (PMID 28498847, 2017). "To examine infection of cultured mature CD14+ CD16+ monocytes, we obtained high numbers of primary CD14+ CD16+ monocytes using a culture method we described previously." (PMID 29066542, 2017). "Levels of IP-10, MCP-1, BAFF, soluble (s)CD14, tumor necrosis factor receptor-2 (TNFR2), and TRAIL were highly overexpressed at the first month of infection (M1) and underwent a prompt decrease in the subsequent months." (PMID 29354131, 2017). "Depletion of CD14+Siglec-1hiCD4+MDM or a decrease in their percentage, resulted in increased infection of MDM, suggestive of a capacity of these cells to capture and sequester HIV-1 in an environment that hinders its infectivity." (PMID 29123518, 2017). "Although the CD14+Siglec-1hiCD4+MDM captured significantly more HIV-1, infection was significantly higher in the CD14+Siglec-1LoCD4−MDM subset." (PMID 29123518, 2017). "Classical monocytes (CD14++CD16–), which comprise peripheral blood monocytes, can migrate to injury and infection sites, where they differentiate into inflammatory macrophages." (PMID 29137628, 2017). "Many markers that are supposed to be involved in the activation of CD14, TLR4, and TLR2 on monocytes and macrophages during infections have also been studied." (PMID 27252945, 2016). "We investigated whether infection of THP-1 macrophages by BCG-OtsB2 was associated with changes in cell-surface expression of a number of immune-related receptors including a number of receptors such as TLR2, TLR4, Mincle, Dectin-1 and CD-14 that have been implicated in phagocytosis of mycobacteria." (PMID 27867377, 2016). "A statistically significant 2-fold increase in CD11c− cDC, CD14+ monocytes, and 3-fold increase in the frequency of and CD4+MHC class II− pDC was observed after infection." (PMID 27008425, 2016).
infection (continued). "Upon infection with FMDV strain O1 Manisa, there was a marked increase in the four DC subsets and CD14+ monocytes, with a peak in cell frequency detected between day 3 and 4 post-infection." (PMID 27008425, 2016). "There are many studies evaluating the relationship of CD14, TLR2, and TLR4 in various infections of adults." (PMID 27252945, 2016). "We report that the frequency of the DC subsets and CD14+ monocytes increased during FMDV infection, and peaked at day 3 to 4 post-infection." (PMID 27008425, 2016). "Mock-infected and DV2-infected PBMC were harvested on day 3 post-infection and stained for TLR2/TLR6 and CD14." (PMID 26226614, 2015). "Eight genes (NCF4, CD14, IL17D, CD1D, CD163, IL1R2, TLR9, and TLR2) with different expression in each infection group were selected for qPCR analysis." (PMID 25906258, 2015). "Compared to pre-infection levels, we found increased BST2 expression in PBMC, purified CD4+ lymphocytes and CD14+ monocytes of SIV-infected animals, which correlated with viral load." (PMID 26554913, 2015). "In acute infection, there was an increase in CD14++CD16+ and CD14+CD16++ monocytes, while CD14++CD16− monocytes decreased two weeks after infection." (PMID 25835530, 2015). "Examination by flow cytometry of the numbers of CD14+ monocytes and WC1+, CD4+ and CD8+ T cells in peripheral blood following infection showed only a transient reduction in the proportion of CD4+ cells at 4 dpi." (PMID 24559207, 2014). "The expression levels of CD14 and CD16 on monocytes were investigated with relation to infection status." (PMID 25101623, 2014). "Consistent with the kinetics of expression of the molecular markers of macrophage activation, a significant percentage of CD14+ cells produced TNF-α in the lungs and spleen (10.5% and 9.1% respectively) of CDC1551 infected rabbits at 4 weeks post infection." (PMID 23448601, 2013). "At three days post infection of CD34 (+) cells only a subset of genes were expressed, whereas in CD14 (+) cells almost the entire HCMV genome showed active transcription." (PMID 23717203, 2013). "CD14 (+) cells were infected with FIX BAC virus and cells where harvested at 3-days post infection or during latency at 15 days post infection." (PMID 23717203, 2013). "We show a key role for CD14 monocytes in the control of antiviral type I IFN responses to RSV via a direct antibody mediated and an indirect, infection mediated, mechanism." (PMID 24303065, 2013). "HCMV initial infection is followed by the establishment of latency in CD34 (+) myeloid cells and CD14 (+) monocytes." (PMID 23717203, 2013). "These analyses revealed that at several time points post-infection, GFP + HIV-infected macrophages were significantly enriched in the CD14+ fraction (3 to 5-fold, p = .0001) compared to bystander, or uninfected cells in the same culture." (PMID 24341794, 2013). "Based on analyses of the mean fluorescent intensity (MFI) for CD14, significantly higher density of this receptor was detected on HIV-GFP + MDM compared to bystander cells at day 14 after infection." (PMID 24341794, 2013). "Before infection, the immature DC phenotype (CD1a +, HLA-DR +, CD80 −, CD86 −, CD14 −, CD83−) was verified by flow cytometry (Figure A1)." (PMID 23970881, 2013). "CD14 (+) monocytes were infected with FIX BAC virus and cells were harvested at 4 and 18 days post infection." (PMID 23717203, 2013). "Viral RNA levels in CD14+ cells and plasma were significantly higher in DHF compared to DF, and in cases with a secondary infection compared to those undergoing a primary infection." (PMID 23284680, 2012). "In contrast, the levels of UL138 transcript expression in FIX-ΔLUNA infected HF and CD14+ cells was 100 and 1000 fold lower (respectively) when compared to the levels observed for FIX-WT infection." (PMID 23300789, 2012).